IFNAR2 (interferon alpha and beta receptor subunit 2)
Diseases named in the same sentence as IFNAR2 in open-access papers (continued):
Sharing a sentence is not in itself a finding about the gene and the disease.
tumor (57 papers, 2005 to 2025). "The results indicated that, in comparison with the control group, mice in the IFNAR2 knockdown group exhibited a significant reduction in tumor volume and prolonged survival time within 30 days." (PMID 41169364, 2025). "We then utilized a U87 orthotopic xenograft mouse model to further assess the effects of IFNAR2 gene inhibition on tumor development in mice." (PMID 41169364, 2025). "Extensive experimental results have verified the fundamental impact of IFNAR2 on fostering tumor proliferation." (PMID 41169364, 2025). "Anti-tumor activity of hCD38-hAtt in these xenograft tumor models did not directly correlate with the levels of expression of CD38 or IFNAR2 of these tumor cell lines in vitro." (PMID 40315226, 2025). "In both, long-term IFN selection and in dedifferentiated tumour cell lines, we found IFNAR2 expression to be substantially reduced, suggesting the receptor complex to be a sensitive target amenable to immunoediting." (PMID 38066598, 2023). "The result showed no significant change in the expression status (data not shown), suggesting that the chemoresistance induced by miR-21 is different from the relationship between the anti-tumour effect and IFNAR2 and EpCAM expression." (PMID 20978511, 2010). "In M0 cases, the normal cells showed moderate reactions and the tumor cells showed weak to moderate reactions for IFNAR2." (PMID 17697365, 2007). "Our data show that there is a upregulation of IFNAR2 mRNAs and IFNAR2c proteins in tumor cells in M1 cases relative to M0 cases." (PMID 17697365, 2007). "In 2000 at age 78 years, the patient also underwent a partial right nephrectomy with a 1 cm surgical margin for another 1.5 cm, grade 1 RCC tumor, and the IFNAR2 mRNA T/N ratio in the resected tissue was 13.3." (PMID 17697365, 2007). "Finally, through genetic analyses and in vitro/in vivo functional experiments, we preliminarily delineated the multifaceted regulatory interventions of IFNAR2 in tumor initiation and progression." (PMID 41169364, 2025). "Moreover, across all ten examined hepatic tumour cell lines we observed a highly significant correlation of IFNAR2 expression with sensitivity to the antiproliferative effect of IFN-β." (PMID 38066598, 2023). "By sharp contrast, Il12p40- and Ifnar2-doubly deficient mice failed to display anti-tumor effects of K3-SPG." (PMID 27384490, 2016). "IFN-α/5-FU combination therapy is a promising modality for advanced HCC with tumour thrombi in the major portal branches and could significantly depend on IFNAR2 expression." (PMID 16106266, 2005). "By integrating bulk transcriptomic and single-cell data along with preliminary functional validation of IFNAR2, our findings suggest that mitophagy receptor signaling may modulate immune functions within the tumor microenvironment, such as macrophage polarization and T cell activity." (PMID 41169364, 2025). "CXCL10, P2RX7, TLR3, and TLR4 were significantly upregulated in IS2 tumours in the TCGA cohort, whereas ANXA1, CXCL10, FPR1, IFNAR2, P2RX7, and TLR4 showed significantly higher expression levels in IS4 tumours in the GEO cohort." (PMID 36851274, 2023). "Through the reduction in expression of IFNAR2 in pSC's surface, inadequate formation and maintenance of the BTB could occur, causing a breakdown of this filter between the testis and the blood, thus explaining higher presence of signals of tumor development in serum." (PMID 33251139, 2020). "Based on their functions, the literature and their occurrence within the candidate deleted FMCR, we propose RASSF3, IFNAR1, IFNAR2 and NFKBIA as novel candidate CRC tumour suppressor genes." (PMID 24367615, 2013). "Increased expression of Ifngr1, Ifngr2 and Ifnar2 in cluster 0 of the CAR-T-treated group (compared to mock-T-treated), indicates this could be a tumor adaptive mechanism to Ifn-γ and Ifn-α signaling mediated by CAR-T cell therapy." (PMID 40568084, 2025).
tumor (continued). "Tumor cell death characterized by CD45 negative dead tumor cells in the spleen after intravenous K3-SPG treatment were significantly reduced in Il12p40 and Ifnar2-doubly deficient mice." (PMID 27384490, 2016). "The anti-tumor effect of K3-SPG was partially reduced in mice lacking Ifnar2, but not in mice lacking Il12p40." (PMID 27384490, 2016). "ONECUT1, ADAMTS, IFNAR2, MSR1, and SORL1 affect migration or metastasis, a process that involves attachment of tumor cells to the basement membrane, degradation of local connective tissue, and penetration and migration of tumor cells through stroma." (PMID 23151184, 2012). "The absolute level of mRNA expression for IFNAR1 and IFNAR2 in the tumor and non-tumor tissues did not correlate with the malignant and the metastatic profiles of the RCC tumors." (PMID 17697365, 2007). "In this study, the relative value of T/N but not the absolute level of IFNAR2 mRNA, and IFNAR2c protein in tumor tissues correlated with the malignant and metastatic profiles of RCC." (PMID 17697365, 2007). "The absolute level of IFNAR1 and IFNAR2 mRNAs in tumor and non-tumor tissues did not correlate with the malignant and metastatic profiles." (PMID 17697365, 2007). "We quantified IFNAR mRNA expression in paired tumor and non-tumor samples from the surgical specimens of 103 consecutive patients with RCC using a real-time reverse transcription polymerase chain reaction (RT-PCR), and IFNAR2 protein using Western blotting." (PMID 17697365, 2007). "To mimic IFN conditions in the tumor microenvironment (TME), we added IFNγ exogenously in SCC cells since (i) IFNγ pathway is the most significant pathway negatively regulated by TP63, (ii) IFNγ receptors (IFNGR1, IFNGR2) have higher expression than IFNα receptors (IFNAR1, IFNAR2) in SCC cells." (PMID 38509096, 2024). "IFNAR1 and IFNAR2 mRNAs were detected in tumor and non-tumor kidney specimens." (PMID 17697365, 2007). "However, our observation that the relative value of the T/N ratio but not the absolute level of IFNAR2 mRNA in tumor tissues correlated with the malignant and metastatic profiles of RCCs is puzzling even if there is inter-individual variations and should be investigated in future studies." (PMID 17697365, 2007). "Since inter-individual variations in the expression of IFNAR mRNAs may be important, the relative yield of the PCR product from the tumor to that from the corresponding non-tumor tissue (T/N) for expression of IFNAR1 and IFNAR2 was calculated as previously." (PMID 17697365, 2007). "Upregulation of IFNAR2 in tumor cells compared to normal cells in the involved kidney might be advantageous for the anti-cancer effect of IFN-α; however, there have been no published reports of a direct relationship between IFNAR2 expression levels and the effect of externally administered IFN-α." (PMID 17697365, 2007).
cancer (30 papers, 2005 to 2025). A tumor composed of atypical neoplastic, often pleomorphic cells that invade other tissues. "Therefore, it appears that IFNAR2 is associated with an aggressive and high metastatic potential of the cancer cells." (PMID 17697365, 2007). "Unexpectedly, we also identified novel IFNAR2-dependent IRGs which are enriched in pathways related to cancer." (PMID 28793350, 2017). "While IFNAR2 proteins were moderately to intensely expressed in the cytoplasm of cancer cells in the M1 cases, these proteins were very weakly expressed by immunohistochemistry in normal cells in M1 cases." (PMID 17697365, 2007). "Interferon-α suppresses the proliferation of all type I interferon receptor 2 (IFNAR2)-positive cancer cell lines in vitro through mechanisms related to apoptosis or inhibition of cell cycle." (PMID 16106266, 2005). "It clearly supports the hypothesis of IFN-driven immunoediting at the cancer cell-intrinsic level, and establishes IFNAR2 as a sensitive target." (PMID 38066598, 2023). "However, analysis of the Cancer Genome Atlas (TCGA) database revealed high expression of Ifnar1 and Ifnar2 in a range of cancer entities and human cancer cell lines showed expression of Ifnar1 and Ifnar2." (PMID 28248314, 2017). "Rs4801778-T (PLEKHA4), rs11919389-C (ZBTB11), rs13050728-C (IFNAR2), and rs10774671-A (OAS1) exhibited a positive or negative regulation in TULP2, HSD17B14, LOC285359, LOC100009676, SENP7, IFNAR2, OAS3, and OAS1 in multiple cancer types." (PMID 35082790, 2021). "Since IFN type I and IFN type II can induce the expression of PD-L1 in cancer cells, we also use siRNAs targeting IFNAR2 or IFNGR1 to silence expression of IFNAR2 or INFGR1 in HCC cells." (PMID 31379842, 2019). "It was previously shown that the fusion of IFNα mutein IFNα R149A, with a 200-fold reduced affinity for the IFNAR2, to a cancer-directed antibody is less likely to bind to IFNAR expressed on normal cells, thus potentially reducing deleterious off-cancer side effects while ‘en route’ to cancer cells." (PMID 40243928, 2025).
neurological diseases (2 papers, 2022). "We first examined the potential antiviral role of IFNAR2 in vitro, by comparing the ability of primary fibroblasts isolated from WT and IFNAR2−/− fetuses to inhibit the replication of ZIKV, a zoonotic flavivirus that can infect both humans and animals and cause a variety of neurological diseases." (PMID 36246651, 2022).
infectious disease (1 paper, 2022). A disorder directly resulting from the presence and activity of a microbial, viral, or parasitic agent in humans. "Establishment of a breeding herd of IFNAR2+/− ewes has greatly facilitated production of IFNAR2−/− sheep for infectious disease and reproductive studies." (PMID 36246651, 2022).
IFNAR2 also shares sentences with these, for which no sentence is quoted: viral disease (6 papers); dengue (5); rubella (4); colitis (3); lymphoma (3); respiratory failure (3); Stroke (3); AIDS (2); allergic reactions (2); Alzheimer disease (2); Crohn disease (2); lung carcinoma (2); ovarian carcinoma (2); renal carcinoma (2); type 1 diabetes (2); achromatopsia (1); acute monocyte leukemia (1); acute respiratory distress syndrome (1); adenocarcinoma (1); adenoma (1); Allergy (1); antisocial/borderline personality disorder (1); Arthritis (1); asthma (1); atherosclerosis (1); B-cell lymphoma (1); bacteremia (1); bacterial infection (1); behavioral disorders (1); bladder cancer (1).
A further 66 diseases each share a sentence with IFNAR2 in 1 paper.